USP18 (ubiquitin specific peptidase 18)
Diseases named in the same sentence as USP18 in open-access papers (continued):
Sharing a sentence is not in itself a finding about the gene and the disease.
heart failure (2 papers, 2024 to 2025). Inability of the heart to pump blood at an adequate rate to meet tissue metabolic requirements. "Recent studies have illustrated that USP18 can inhibit cardiac remodelling and arrest the development of heart failure through the TAK1‐p38/JNK1/2 signalling pathway." (PMID 39804798, 2025). "Among these, Ubiquitin‐specific protease 18 (USP18) has emerged as a potential therapeutic target for heart failure." (PMID 39804798, 2025). "USP18 plays a well-described protective role in the development of heart failure but its role in kidney injury remains unrecognized." (PMID 38791035, 2024). "Another role of USP18 is its contribution to the cardiac muscle remodeling and development of heart failure." (PMID 38791035, 2024). "Experiments performed in transgenic mice demonstrated that the increased USP18 expression in cardiomyocytes upon an increased afterload attenuated the cardiomyocyte hypertrophy and myocardial fibrosis, resulting in the delayed development of heart failure." (PMID 38791035, 2024). "Several papers described the role of USP18 in cardiomyocyte damage, but its role in kidney injury remains unknown, though bidirectional cardio-renal interactions are well recognized in the pathophysiology of chronic kidney disease and heart failure." (PMID 38791035, 2024).
Hepatic steatosis (2 papers, 2023 to 2025). Steatosis is a term used to denote lipid accumulation within hepatocytes. "Mechanistically, USP18 mitigates hepatic steatosis by interacting with and deubiquitinating TGFβ‐activated kinase 1 (TAK1), thereby inhibiting its activation and consequently suppressing the downstream JNK and NF‐κB signalling pathways." (PMID 39804798, 2025).
ischaemic stroke (2 papers, 2025). "In response to ischemic stroke, neurons initiate a protective mechanism involving ubl carboxyl-terminal hydrolase 18 (USP18), which stabilizes the fat mass and obesity-associated protein (FTO) through deubiquitination, leading to increased FTO protein levels." (PMID 40705152, 2025).
ischemia (2 papers, 2016 to 2022). A hypoperfusion of the BLOOD through an organ or tissue caused by a PATHOLOGIC CONSTRICTION or obstruction of its BLOOD VESSELS, or an absence of BLOOD CIRCULATION. "Hepatic ischemia/reperfusion injury led to an induction of USP18 expression in liver tissue and promotion of lymphocytic choriomeningitis replication." (PMID 27009955, 2016). "In our present study, hepatic ischemia/reperfusion injury did not enhance LCMV production in USP18 knockout mice." (PMID 27009955, 2016).
leukodystrophies (2 papers, 2021 to 2024). "Leukodystrophies related to bi-allelic loss-of-function mutations in CSF1R, TREM2, TYROBP, LRRC33/NRROS or USP18 can be categorized as primary microgliopathies." (PMID 34282843, 2021). "Although the pathology of USP18-related leukodystrophy or the reason why microglia are selectively affected are unclear, we hypothesize that USP18-related leukodystrophy and AGS could share similar mechanisms." (PMID 38129659, 2024). "Defective neuronal migration is observed in USP18-related leukodystrophy patients." (PMID 34282843, 2021).
Listeria infection (2 papers, 2015 to 2019). "Since USP18 is concomitantly induced with ISG15 following Listeria infection, we suspect that certain substrates are deconjugated more rapidly than others." (PMID 31772204, 2019). "We found that UBE1L (E1), UBE2L6 (E2), HERC5 and TRIM25 (E3s) mRNA are all significantly upregulated following Listeria infection, as is the deconjugating enzyme USP18." (PMID 26259872, 2015). "USP18 is concomitantly upregulated with ISG15 following Listeria infection and whether this is to temporally regulate specific targets or to alter STAT signaling remains to be determined." (PMID 31772204, 2019). "Since USP18 deletion cannot distinguish between these functions, we first assessed whether the deconjugase-dead (USP18C61A/C61A) mouse would be resistant to Listeria infection." (PMID 31772204, 2019).
liver fibrosis (2 papers, 2025). "Additionally, USP18 inhibits hepatic stellate cell activation and alleviates liver fibrosis by regulating TAK1 activity through ubiquitination." (PMID 40170095, 2025). "In this study, IFNα, IFNβ, ISG15, USP18, IFN-induced protein 44 (Ifi44), interferon-induced protein with tetratricopeptide repeat (Ifit) 1, Ifit2, IRF3, and IRF7 were significantly elevated in the CCl4-induced liver fibrosis model." (PMID 40260261, 2025).
Obesity (2 papers, 2023 to 2025). Accumulation of substantial excess body fat. "Using the same in vivo model systems, it was shown that ubiquitin-specific peptidase 18 (USP18) and fat mass and obesity-associated protein (FTO) expression decreased after OGD/R." (PMID 40724883, 2025).
sarcoma (2 papers, 2014 to 2015). A usually aggressive malignant neoplasm of the soft tissue or bone. "Given this, we sought to treat USP18 null sarcoma cell lines with IFNβ to determine if they exhibited type I IFN hypersensitivity." (PMID 26555296, 2015). "Defects in IFN signaling can augment tumorigenesis in the 3-MCA-sarcoma model; evidence from USP18 null mice identified an amplified IFN response as compared to wild-type mice, which is thought to provide a less permissive environment for tumors." (PMID 26555296, 2015). "USP18 expression in tumor cells, such as human sarcoma 2fTGH cells, is not only induced by IFNγ timulation." (PMID 24884733, 2014). "Abundant USP18 immunostaining in vascular smooth muscle cells implied that sarcomas seen in these mice could be of vascular origin." (PMID 26555296, 2015). "The sarcomas occurred in USP18 null mice as early as 2 months of age." (PMID 26555296, 2015). "Tumor histology was similar to the sarcomas in USP18 null mice." (PMID 26555296, 2015). "Most of the USP18 knockout mice exhibited palpable sarcomas at ages from 6 months to 12 months." (PMID 26555296, 2015). "While loss of USP18 preceded sarcoma formation, these sarcoma cell lines did not depend on loss of USP18 expression for survival, growth or tumorigenicity." (PMID 26555296, 2015). "Decrease in USP18 has not been previously associated with sarcoma development." (PMID 26555296, 2015). "Restoration of USP18 activity in sarcoma-derived cell lines did not reduce anchorage dependent or independent growth or xenograft tumor formation demonstrating that these cells no longer require USP18 suppression for tumorigenesis." (PMID 26555296, 2015).
Sepsis (2 papers, 2021 to 2024). Sepsis is defined as life-threatening organ dysfunction caused by a dysregulated host response to infection. "A latest study showed that TAK1 could be targeted by ubiquitin-specific peptidase 18, negatively regulating and inhibiting LPS-induced sepsis." (PMID 34938184, 2021).
anemia (1 paper, 2022). A reduction in the number of red blood cells, the amount of hemoglobin, and/or the volume of packed red blood cells. "Anemia was seen in nearly half of the SLE patients in this study, and the expression levels of RSAD2, USP18, and IFI44 were lower in those patients." (PMID 35967341, 2022).
bladder tumors (1 paper, 2021). "Up-regulation of USP18 was further confirmed in patient-derived bladder tumors in this study." (PMID 33461172, 2021).
brain injuries (1 paper, 2018). "USP18 knockout mice (USP18−/−) were described to develop brain injuries and show reduced life expectancy." (PMID 30126853, 2018).
cervical squamous cell carcinoma (1 paper, 2020). A squamous cell carcinoma arising from the cervical epithelium. "The level of USP18 was substantially higher in cervical squamous cell carcinoma (CESC) samples than that in para-cancer samples." (PMID 32770981, 2020).
chronic hepatitis C (1 paper, 2015). "The expression levels of a subset of eight genes, including dual specificity phosphatase 1 (DUSP1) and ubiquitin-specific protease 18 (USP18), have previously been used to predict the treatment response of patients with chronic hepatitis C." (PMID 25798824, 2015).
chronic kidney disease (1 paper, 2024). Impairment of the renal function secondary to chronic kidney damage persisting for three or more months. "The objective of the study was to assess the relationship between serum and urine USP18 levels, the factors contributing to cardiovascular risk, and the markers of kidney disease activity at different stages of chronic kidney disease (CKD)." (PMID 38791035, 2024).
COPA syndrome (1 paper, 2023). "Functional mutations of the USP18 gene can cause TORCH syndrome, while Proteasome-associated autoinflammatory syndrome (PRAAS) and COPA syndrome are also linked to dysregulation of the INFβ pathway." (PMID 37396372, 2023).
dermatomyositis (1 paper, 2023). Dermatomyositis (DM) is a type of idiopathic inflammatory myopathy characterized by evocative skin lesions and symmetrical proximal muscle weakness. "USP18 expression was also found in Dermatomyositis, a muscular inflammatory disease." (PMID 37002195, 2023). "In dermatomyositis, both USP18 and ISG15 are upregulated in inflamed muscle tissue regions." (PMID 37002195, 2023).
Down syndrome (1 paper, 2024). "In line, USP18 has been suggested to participate in similar mechanisms of inhibition of type I IFN priming in the context of Down syndrome patients." (PMID 38953896, 2024). "Interestingly, USP18 upregulation has been shown to contribute to the hyporesponsiveness of cells from Down syndrome patients to a second IFN stimulation." (PMID 38953896, 2024).
Encephalopathy (1 paper, 2025). Encephalopathy is a term that means brain disease, damage, or malfunction. "This case of USP18 deficiency demonstrates the devastating neonatal course of pseudo-TORCH syndromes and reinforces their inclusion in the differential diagnosis of encephalopathy, intracranial calcifications, and negative infectious evaluations in infants." (PMID 40937018, 2025).
endotoxemia (1 paper, 2020). "Finally, we identified and verified 9 key genes (Cd274, Cxcl1, Cxcl9, Icam1, Ifit2, Isg15, Stat1, Tlr2, and Usp18), and we predicted seven potential drugs for multi-organ damage in LPS-induced endotoxemia." (PMID 33330617, 2020).
Erythema (1 paper, 2022). Redness of the skin, caused by hyperemia of the capillaries in the lower layers of the skin. "The expression levels of NRIR, USP18, and IFI44 in PBMCs of SLE patients with facial erythema were significantly higher than those in SLE patients without facial erythema." (PMID 35967341, 2022).
Flavivirus Infections (1 paper, 2024). Infections with viruses of the genus FLAVIVIRUS, family FLAVIVIRIDAE. "Here we provide mechanistic insight of the arms race between ISG15, USP18 and NS5 which suggests that protein/protein dynamics adjacent to IFNAR are a key determinant for the outcome of flavivirus infection." (PMID 38384473, 2024). "Moreover, USP18 competes with NS5-mediated STAT2 degradation, a major mechanism for establishment of flavivirus infection." (PMID 38384473, 2024).
Hepatitis B (1 paper, 2022). "USP18 is capable of attenuating Type 1 Interferon signaling, which has been associated with persistence of both Hepatitis B and C infection in liver." (PMID 35784346, 2022).
Hypercholesterolemia (1 paper, 2025). An increased concentration of cholesterol in the blood. "Our analysis revealed that patients with FH exhibit a notably higher level of USP18 expression compared to those without hypercholesterolemia as illustrated by the heatmap and volcano plot." (PMID 39804798, 2025).
Hypertension (1 paper, 2023). The presence of chronic increased pressure in the systemic arterial system. "Hypertension is frequently associated with cardiac dilation and hypertrophy, and USP18 expression was found to be high both in dilated human hearts and in hypertrophic mice." (PMID 37025175, 2023).
intracranial hemorrhage (1 paper, 2021). Bleeding within the SKULL, including hemorrhages in the brain and the three membranes of MENINGES. "USP18 deficiency in neonate leads to a severe pseudo-TORCH syndrome, showing manifestation such as perinatal-onset intracranial hemorrhage, calcifications, brain malformations without detectable pathogen." (PMID 34016972, 2021).
liver cancer (1 paper, 2020). An epithelial or non-epithelial malignant neoplasm that arises from the liver. "USP18 is also involved in the development of breast, lung and liver cancers 19-21." (PMID 32132870, 2020). "In conclusion, our study shows that expression of EFP, HERC5, UBA1 and USP18 genes, upregulated in tumour tissues of HCC patients, is correlated with liver function parameters and, thus, may be associated with the pathogenesis of liver cancer." (PMID 32132870, 2020).
lymph node metastasis (1 paper, 2024). "In the context of lymph node metastasis, USP18 expression was significantly higher in early (N0 stage) COAD and READ tissues than in normal tissues, suggesting that USP18 could be used as a biomarker for the early detection of CRC." (PMID 39334957, 2024).
MELAS (1 paper, 2023). "In IRF2 targets, which were significantly enriched in MELAS subjects, Polg mice, and Tfam± MEFs, USP18, TAP1, BST2, IFI35 were consistently increased." (PMID 37208779, 2023).
mesothelioma (1 paper, 2023). A usually malignant and aggressive neoplasm of the mesothelium which is often associated with exposure to asbestos. "The expression and chromatin analyses at genes such as USP43, HOXA6, HOXA10, and USP18 demonstrate that these genes are downregulated via PRC2-mediated silencing in BAP1-deficient mesothelioma." (PMID 36657447, 2023).
mucinous adenocarcinoma (1 paper, 2024). An invasive adenocarcinoma composed of malignant glandular cells which contain intracytoplasmic mucin. "In addition, the expression of USP18 was significantly different across different histologic types and lymph node metastasis statuses (normal versus interstitial/mucinous adenocarcinoma in COAD patients, p = 0.0001438/0.004078; normal versus adenocarcinoma in READ patients, p = 0.003756)." (PMID 39334957, 2024).
myeloid leukemia (1 paper, 2023). A clonal proliferation of myeloid cells and their precursors in the bone marrow, peripheral blood, and spleen. "We first evaluated whether heterozygous Usp18 deletion sensitized myeloid leukemia cells to IFN stimulation." (PMID 36646704, 2023).
myositis (1 paper, 2023). "Engineered muscle bundles combined with inflammatory cells, could present a relevant model to explore the role of USP18 in myositis." (PMID 37002195, 2023).
nonalcoholic steatohepatitis (1 paper, 2020). "Interestingly, USP18 expression has been shown to be downregulated in the livers of nonalcoholic steatohepatitis (NASH) patients." (PMID 32957626, 2020).
osteoporosis (1 paper, 2024). A condition of reduced bone mass, with decreased cortical thickness and a decrease in the number and size of the trabeculae of cancellous bone (but normal chemical composition), resulting in increased fracture incidence. "The USP18 emerges as a potential therapeutic target for osteoporosis treatment, highlighting the importance of the hypoxia–DUB axis in the pathogenesis of the disease." (PMID 39795869, 2024). "Considering the pivotal role of the NF-κB signaling pathway in the development of various endocrine system disorders, particularly osteoporosis, we conducted immunoblotting to detect the activation/phosphorylation of p65 under varied USP18 expression conditions." (PMID 39795869, 2024). "Thus, hypoxia might weaken the USP18-mediated suppression of the NF-κB signaling pathway to significantly promote osteoclast differentiation, consequently participating in osteoporosis development." (PMID 39795869, 2024).
pancreatic cancer (1 paper, 2020). "In the present study, we aimed to investigate the prognostic values and biological functions of USP18 and its associated molecular mechanisms in pancreatic cancer." (PMID 33051403, 2020). "We first evaluated the expression level of USP18 in pancreatic cancer tissues and investigated the association of the USP18 expression level with clinicopathological features and patient survival." (PMID 33051403, 2020). "The results showed that the donwnregulation of Notch1 inhibited the increases in c-Myc expression observed in USP18-overexpressing pancreatic cancer cells." (PMID 33051403, 2020). "Previous studies have demonstrated that c-Myc is a key regulator of pancreatic cancer cell proliferation, and RNA-seq data have indicated that c-Myc is down-regulated in USP18-knockdown cells." (PMID 33051403, 2020). "First, our results demonstrated that USP18 regulates c-Myc protein expression to influence pancreatic cancer progression." (PMID 33051403, 2020). "Next, we analysed the relationship between USP18 expression and clinicopathological factors in 108 pancreatic cancer patients." (PMID 33051403, 2020). "To determine the role of USP18 in the aggressiveness of pancreatic cancer, we firstly examined USP18 expression in pancreatic cancer tissues and corresponding adjacent tissues by qRT-PCR." (PMID 33051403, 2020). "Scatter plots revealed that USP18 and Notch1 protein expression levels were positively correlated in pancreatic cancer tissues." (PMID 33051403, 2020). "The results showed that USP18 expression was increased in pancreatic cancer tissues compared with normal tissues." (PMID 33051403, 2020). "A functional assay demonstrated that overexpression of USP18 resulted in increased proliferation of pancreatic cancer cells." (PMID 33051403, 2020). "Scatter plots revealed that USP18 and c-Myc protein expression levels were positively correlated in pancreatic cancer tissues." (PMID 33051403, 2020). "In conclusion, these data collectively indicated that USP18 contributes to growth of pancreatic cancer cells in vitro and in vivo." (PMID 33051403, 2020). "Multivariate analyses further revealed that high USP18 expression was an independent predictive factor for poor OS in pancreatic cancer." (PMID 33051403, 2020). "To further verify that USP18 regulates c-Myc expression through Notch1 in pancreatic cancer cells, we decreased the expression of Nothc1 in USP18-overexpressing pancreatic cancer cells and then observed the Nothc1 and c-Myc protein levels." (PMID 33051403, 2020). "Here, we found that the deubiquitinase ubiquitin-specific protease 18 (USP18) is significantly upregulated in pancreatic cancer and is correlated with a shorter median overall and relapse-free survival." (PMID 33051403, 2020). "To investigate the potential biological function of USP18 in pancreatic cancer development, we first determined USP18 expression in pancreatic cancer cell lines." (PMID 33051403, 2020). "Then, we studied the role of USP18 in the progression of pancreatic cancer in both in vivo and in vitro models." (PMID 33051403, 2020). "The CCK8 and EdU assay data showed that silencing USP18 obviously suppressed pancreatic cancer cell growth in vitro." (PMID 33051403, 2020). "In the present study, our results revealed that USP18 is an oncogene in pancreatic cancer and provides a potential druggable target for this intractable disease." (PMID 33051403, 2020). "Both in vivo and in vitro data demonstrated that USP18 knockdown impaired cell proliferation in pancreatic cancer." (PMID 33051403, 2020). "Next, we further examined the expression levels of USP18 in the pancreatic cancer tissues using Western blot." (PMID 33051403, 2020). "Our work identifies and validates USP18 as a pancreatic cancer oncogene and provides a potential druggable target for this intractable disease." (PMID 33051403, 2020).